RAMP1 (receptor activity modifying protein 1)
Diseases named in the same sentence as RAMP1 in open-access papers (continued):
Sharing a sentence is not in itself a finding about the gene and the disease.
adenomyosis (2 papers, 2019 to 2021). The growth of endometrial tissue inside the muscular wall of the uterine corpus. "Adenomyotic tissue samples from 30 women with adenomyosis and control endometrial tissue samples from 24 women without adenomyosis were collected and subjected to immunohistochemistry analysis of RAMP1, CRLR, NK1R, ADRB2 and α7nAChR, along with their demographic and clinical information." (PMID 33602248, 2021). "For endometriotic lesions, the NK1R, RAMP-1, and CRLR staining levels were significantly higher in DE lesions than OE lesions, even after the adjustment for age, menstrual phase, parity, presence or absence of adenomyosis, and presence or absence of uterine fibroids (all p-values < 0.008)." (PMID 30804432, 2019).
allergic asthma (2 papers, 2014 to 2025). A asthma with a basis in a pathological type I hypersensitivity reaction. "In summary, we have shown that a loss of RAMP1 signaling in a model of allergic asthma results in improvements in both airway resistance and inflammation after challenge." (PMID 25010197, 2014). "Together, these findings suggest a model in which CGRP alleviates allergic asthma primarily through RAMP1-mediated regulation of CD4+ T cells during the sensitization phase." (PMID 41472747, 2025). "Additionally, Calca−/−, Ramp1−/−, and CD4+ T cell-specific RAMP1 knockout mice were used from immunological studies in the HDM-induced allergic asthma model." (PMID 41472747, 2025). "Additionally, a reduction of CLR in the lung also reduced the airway resistance, indicating that the CLR/RAMP1 complex, which is the receptor for CGRP, is a major mediator of pathological signals in allergic asthma." (PMID 25010197, 2014). "Finally, we report that endothelial as well as inflammatory cells within the lung express both RAMP1 and CLR, indicating that action of CGRP on these cell populations may contribute to the observed pathology in this model of allergic asthma." (PMID 25010197, 2014).
COVID-19 (2 papers, 2022 to 2023). A disease caused by infection with severe acute respiratory syndrome coronavirus 2. "On the other hand, the Ochoa-Callejero research group showed low serum CGRP levels in COVID-19 patients, along with an increased lung RAMP1 expression, which is supposed to compensate for the decrease in systemic CGRP levels." (PMID 36298678, 2022).
gastric cancer (2 papers, 2017 to 2022). A primary or metastatic malignant neoplasm involving the stomach. "We screened eight DDR-related genes (ZBTB7A, POLQ, CHEK1, NPDC1, RAMP1, AXIN2, SFRP2, and APOD) to establish a risk model, which can predict the prognosis of gastric cancer patients and guide the clinical implementation of immunotherapy." (PMID 36578802, 2022). "Our results show that the expression levels of AM, CRLR, RAMP1, RAMP2, and RAMP3 are higher in gastric cancer tissues than in the adjacent non-tumor gastric tissues, and the patients with the lower expression levels of AM lived longer (p=0.0258)." (PMID 29179449, 2017).
acute lung injury (1 paper, 2024). A condition of lung damage that is characterized by bilateral pulmonary infiltrates (pulmonary edema) rich in neutrophils, and in the absence of clinical heart failure. "This study examined the role of RAMP1 signaling during lipopolysaccharide (LPS)-induced acute lung injury (ALI)." (PMID 39337592, 2024).
acute pancreatitis (1 paper, 2022). An acute inflammatory process that leads to necrosis of the pancreatic parenchyma. "Additionally, mice with the receptor activity modifying protein 1, RAMP1, deleted were used to examine the role of CGRP in acute pancreatitis." (PMID 36293102, 2022).
airway hyperresponsiveness (1 paper, 2014). "Together, these data indicate that CLR and RAMP1 are expressed by endothelial, and to some extent inflammatory cells, indicating that CGRP signaling in these cell populations may be responsible for driving the observed airway hyperresponsiveness." (PMID 25010197, 2014).
atopic dermatitis (1 paper, 2026). "In skin barrier tissues, low‐frequency stimulation (<1 Hz) of nociceptive neurons releases CGRP, which binds RAMP1–calcitonin receptor‐like receptor (CLR) receptor complexes on DCs to promote Treg cell differentiation and suppress Th2‐mediated inflammation (e.g., in atopic dermatitis)." (PMID 41583906, 2026).
breast carcinoma (1 paper, 2018). "Less is known regarding the chemokinetic effects of CGRP receptors (RAMP1 and CALCRL), although their expression has been demonstrated in several lines of cancer (e.g., prostate and breast cancer)." (PMID 30598641, 2018).
breast invasive carcinoma (1 paper, 2023). "For instance, research has demonstrated the upregulation of RAMP1 in breast invasive carcinoma (BRCA), prostate adenocarcinoma (PRAD), and liver hepatocellular carcinoma (LIHC)." (PMID 37796823, 2023).
colon adenocarcinoma (1 paper, 2023). "High RAMP1 expression was positively correlated with ESTIMATE Score, Immune Score, and Stromal Score in colon adenocarcinoma (COAD), BLCA and READ (r>0.3, p<0.05)." (PMID 37796823, 2023).
endothelial dysfunction (1 paper, 2022). In vascular diseases, endothelial dysfunction is a systemic pathological state of the endothelium (the inner lining of blood vessels) and can be broadly defined as an imbalance between vasodilating and vasoconstricting substances produced by (or acting on) the endothelium. "These peptides signal through CLR/RAMP1, 2, and 3 receptors, and protect against endothelial dysfunction in disease models." (PMID 36362188, 2022).
Hepatitis (1 paper, 2018). Inflammation of the liver. "RAMP1-deficient mice with concanavalin A (ConA)-mediated hepatitis, characterized by severe liver injury accompanied by infiltration of immune cells and increased secretion of pro-inflammatory cytokines by KCs and splenic T cells, showed poor survival." (PMID 30462657, 2018). "However, ALT levels in splenectomized Ramp1-/- mice fell by 50% at 24 h after ConA treatment when compared with those in sham-operated Ramp1-/- mice, indicating that RAMP1 deficiency in splenocytes contributes to the aggravated ConA-mediated hepatitis." (PMID 30462657, 2018). "Here, we demonstrated that RAMP1 signaling plays an immunosuppressive role in ConA-mediated hepatitis by downregulating production of pro-inflammatory cytokines by KCs and splenic T cells." (PMID 30462657, 2018). "Regarding RAMP1 signaling, splenectomy led to a partial improvement in ConA hepatitis in Ramp1-/- mice, suggesting that RAMP1 signaling in splenocytes participates in ConA-mediated hepatitis." (PMID 30462657, 2018). "RAMP1 signaling inhibits development of ConA-induced hepatitis by inactivating hepatic and splenic immune cells." (PMID 30462657, 2018). "Here, we used RAMP1 knockout (Ramp1-/-) mice to explore the crosstalk between RAMP1 signaling and innate immunity in the liver and spleen during ConA-mediated hepatitis." (PMID 30462657, 2018). "Next, we examined the role of RAMP1 signaling in ConA-induced hepatitis by biochemical and histological evaluation of liver injury." (PMID 30462657, 2018). "To further clarify the role of T cells (CD4+ cells) in ConA hepatitis, we treated WT and Ramp1-/- mice with an anti-CD4 antibody 24 h before ConA treatment." (PMID 30462657, 2018). "Here, we demonstrate that RAMP1 attenuates ConA-mediated hepatitis." (PMID 30462657, 2018). "To further validate the functional role of RAMP1 signaling in T cells in ConA-mediated hepatitis, we transferred WT-CD4+ T cells into Ramp1-/- mice." (PMID 30462657, 2018).
lung adenocarcinoma (1 paper, 2020). A carcinoma that arises from the lung and is characterized by the presence of malignant glandular epithelial cells. "In a study on lung adenocarcinoma, four fusion genes (WISP1, RAMP1, MYBL2, and GATA2) of the human leukocyte antigen (HLA) family were identified by RNA-seq technology, indicating that the HLA family genes might be potential targets for the lung adenocarcinoma therapy." (PMID 32117438, 2020).
lung injury (1 paper, 2024). "In this study, we examined the role of RAMP1 signaling in LPS-induced acute lung injury (ALI) and elucidated the regulatory mechanisms by which RAMP1 signaling participates in the development of ARDS." (PMID 39337592, 2024).
lymphedema (1 paper, 2018). Excess fluid collection in tissues, causing swelling. "CGRP also contributes to wound healing and secondary lymphedema by affecting RAMP1 signaling in macrophages." (PMID 30462657, 2018).
medullary thyroid carcinoma (1 paper, 2014). "Additionally, we show that in human medullary thyroid carcinoma cells (TT), a significant reduction in the signalling of the CaSR when RAMP1 is knocked down or blocked with a RAMP1 antibody." (PMID 24454825, 2014).
metastatic cancer (1 paper, 2018). A carcinoma which has spread from the original site of growth to another anatomic site. "Our data show that NPs strongly modify the chemokinetic capabilities of a cellular line commonly used as a model of metastatic cancer to bone (MDA-MB-231LUC+) and increased the expression of their receptors (NK1R, NK2R, RAMP1, and CALCRL) on these cells." (PMID 30598641, 2018).
Pain (1 paper, 2025). An unpleasant sensory and emotional experience associated with actual or potential tissue damage, or described in terms of such damage. "In a model of neuropathic pain, an increase in CGRP, CLR, and RAMP1 mRNA expression was observed in the central amygdala of female rats compared to males at the chronic phase while males showed an increase of CGRP mRNA expression at the acute phase of neuropathic pain." (PMID 40708951, 2025).
pneumonia (1 paper, 2014). An acute, acute and chronic, or chronic inflammation focally or diffusely affecting the lung parenchyma, caused by an infection in one or both of the lungs (by bacteria, viruses, fungi, or mycoplasma.). "In summary, reduced expression of RAMP1 to RAMP3 under MV in pneumonia was observed, suggesting weakened protection of endothelial integrity due to reduced endogenous AM function." (PMID 24731244, 2014). "Pneumonia resulted in an increase of RAMP1 to RAMP3 expression, while MV markedly reduced mRNA levels of RAMP1 to RAMP3 in pneumonia." (PMID 24731244, 2014). "Notably, treatment with AM did not alter expression of AM, CRLR or RAMP1 to RAMP3 in pneumonia and subsequent MV." (PMID 24731244, 2014).
rectal adenocarcinoma (1 paper, 2023). "High RAMP1 expression levels have consistently been correlated with unfavorable clinical outcomes in rectal adenocarcinoma (READ), including shorter overall survival and decreased DFI and PFI." (PMID 37796823, 2023).
septic arthritis (1 paper, 2025). "The released CGRP then inhibits the production of chemotactic cytokines by CX3CR1+ tissue-resident synovial lining macrophages via receptor activity modifying protein 1 (RAMP1) receptors at the onset of septic arthritis." (PMID 39960341, 2025).
septic peritonitis (1 paper, 2024). Septic peritonitis is an inflammatory condition of the peritoneum that occurs secondary to microbial contamination. "In the early phase of septic peritonitis, RAMP1-deficient mice displayed increased neutrophil levels." (PMID 39337592, 2024).
thyroid carcinoma (1 paper, 2024). "Although expression of these genes was sensitive to loss of IFT57 but not CD47 in thyroid carcinoma cells, a majority showed positive or negative coexpression with CD47 mRNA in the tumors that paralleled their IFT57 coexpression (e.g., RAMP1)." (PMID 39201643, 2024).
uterine corpus endometrial carcinoma (1 paper, 2023). A endometrial carcinoma (disease) that involves the body of uterus. "Conversely, downregulation of RAMP1 has been observed in bladder urothelial carcinoma (BLCA) and uterine corpus endometrial carcinoma (UCEC)." (PMID 37796823, 2023).
tumor (24 papers, 2017 to 2025). "Multivariate Cox regression analysis identified SNPs in 8 genes (Stx6, Ramp1, Traf3ip1, Nckap5, Pfkfb2, Trmt1l, Rprd1b, and Rer1) that were independently associated with age of tumour onset." (PMID 39067134, 2024). "We pooled all 20 genes (Stx6, Ramp1, Traf3ip1, Nckap5, Pfkfb2, Trmt1l, Rprd1b, Rer1, Sepsecs, Rhobtb1, Tsen15, Abcc3, Arid5b, Tnr, Dock2, Tti1, Fam81a, Oxr1, Plxna2 and Tbc1d31) together as the mouse tumour susceptibility gene signature (mTSGS)." (PMID 39067134, 2024). "Additionally, considering the crucial role of immune cell infiltration in the tumor-immune microenvironment during the progression of OS, we further explored the association between the intra-tumoral immune microenvironment and RAMP1 in OS." (PMID 37796823, 2023). "A direct effect of CGRP on tumor growth is suggested, especially through binding to the RAMP 1 component of the receptor; in any case, the CGRP-RAMP1-CRLR complex seems to have a direct effect on tumor cells." (PMID 38674047, 2024). "The CGRP receptor is composed of RAMP1 and CALCR1 and is present in various malignant tumor cells and tumor-associated immune cells." (PMID 38567163, 2024). "This study demonstrated a higher expression of RAMP1 for tumor-infiltrating immune cells (CD4+ T cells, cytotoxic CD8+ T cells, and NK cells) in OSCC patients compared to immune cells from the normal tissue of healthy individuals." (PMID 38334648, 2024). "The analysis conducted using the Tumor Immune Estimation Resource (TIMER) database demonstrated a significant correlation between RAMP1 gene expression and various immune cell populations infiltrating the TME." (PMID 37796823, 2023). "Several studies have investigated the expression levels of the RAMP1 gene across various tumor types." (PMID 37796823, 2023). "The function of RAMP1 in the tumor microenvironment was analyzed, and its expression in OS cell lines was validated using quantitative real-time PCR." (PMID 37796823, 2023). "We evaluated the RAMP1 expression and prognostic value across different cancers, studying tumor immune infiltration." (PMID 37796823, 2023). "Next, we treated tumour-bearing mice with the selective RAMP1 antagonist BIBN4096 (5 mg kg−1, i.p., once every two days)." (PMID 36323780, 2022). "This analysis also revealed that tumour-infiltrating CD8+ cells collected from patients who were resistant to ICIs markedly overexpressed RAMP1." (PMID 36323780, 2022). "Although CALCB and RAMP1 were knocked down to low levels as confirmed by qRT-PCR of tumor tissue, the growth-inhibiting effect was more pronounced in the group of the RAMP1 knockdown." (PMID 30741933, 2019). "Among these, RAMP1 is particularly notable considering its involvement in biological processes and recent evidence highlighting its relationship with neuronal signaling and pro-tumor stimuli in the microenvironment." (PMID 41234433, 2025). "Overall, these findings suggest that targeting the N/OFQ and RAMP1 pathways could bolster anti-tumor immunity while simultaneously alleviating cancer-induced pain." (PMID 40951290, 2025). "In a human cardiomyocyte cell line (a tumor cell line expressing only calcitonin receptor-like receptors and RAMP1), CGRP increased the cAMP level, calcium ion transients, nitric oxide formation, and phosphorylation of the extracellular signal-regulated kinases ERK1/2." (PMID 40085216, 2025). "Blocking RAMP1 reduced tumor growth and promoted B-cell Pnoc expression." (PMID 40951290, 2025). "Our findings suggest that resistance-associated DEGs such as RAMP1, GSG1L, and GRIK4 may contribute to shaping the tumor microenvironment through interactions with M0/M2 macrophages and resting CD4+ memory T cells." (PMID 41234433, 2025). "For example, RAMP1, which encodes a protein that regulates cell proliferation and angiogenesis, had been reported to induce the functional depletion of CD8+ T cells with tumour invasion." (PMID 39294858, 2024).
tumor (continued). "Moreover, many of these genes are associated with stemness, such as MUC5B, as well as tumor biology, including REG4, LYZ, EREG, KRT23, and RAMP1, which were also identified in a previous CRC single-cell study." (PMID 39350339, 2024). "Multivariate analyses flagged SNPs in 20 genes (Stx6, Ramp1, Traf3ip1, Nckap5, Pfkfb2, Trmt1l, Rprd1b, Rer1, Sepsecs, Rhobtb1, Tsen15, Abcc3, Arid5b, Tnr, Dock2, Tti1, Fam81a, Oxr1, Plxna2, and Tbc1d31) independently tied to various tumour characteristics, designated as a mTSGS." (PMID 39067134, 2024). "This subset ultimately acts as a regulator of LCRC aggressiveness, promoting tumor invasion through TGF-β signaling, upregulation of pro-tumor genes (RAMP1, MYLK, MYH11) and activation of muscle-invasive pathways." (PMID 41450739, 2025). "In the tumor microenvironment, CGRP triggers immune exhaustion by stimulating receptor activity-modifying protein 1 (RAMP1) on CD8 T-cells." (PMID 40951290, 2025). "The results showed that the genes (RAMP1, MYLK and MYH11) of cluster 6 end‐stage were enriched with tumour activation pathways such as cell proliferation and angiogenesis." (PMID 39294858, 2024). "By binding with RAMP1, it leads to functional exhaustion of CD8+ T cells and a reduction in their anti-tumor activity." (PMID 38567163, 2024). "Subsequent immunofluorescence double-labelling experiments performed on various CALCRL-positive tumour specimens revealed that RAMP2 expression was predominant, with slightly lower expression of RAMP1." (PMID 36835377, 2023). "Compared to fibroblasts from normal tissues, the top upregulated genes in tumor-derived fibroblasts were CXCL8, CXCL2, CCL2, CXCL3 and CXCL1, and the top downregulated genes were IGFBP5, PTGDS, CCN5, CFD, and RAMP1." (PMID 36357663, 2022). "The angiogenesis cluster—besides containing some of the same previous ECM proteins—comprised the angiopoietin ANGPTL4 and other genes that are known to act in tumour-induced angiogenesis (AQP1, RAMP1, HSPB1, MYLK), for a total of 21 entries." (PMID 34439343, 2021). "Indeed, the pharmacological nociceptor inhibition or blocking of the receptor activity modifying protein 1 (RAMP1), the receptor for CGRP, reduced T cell exhaustion and inhibited tumor growth in a mouse model." (PMID 38334648, 2024). "In the field of tumor research, RAMP1 has been identified as a direct NKX3.1 target gene and a novel biomarker, playing a significant role in promoting prostate carcinogenesis." (PMID 37796823, 2023). "Although we retrieved similar numbers of CD8+ T cells across all three groups, limited B16F10-OVA tumour growth was found in mice that received the Ramp1−/− CD8+ T cells—which are not responsive to CGRP." (PMID 36323780, 2022). "Furthermore, the levels of the AM receptors RAMP1, RAMP2, RAMP3, and CRLR were also elevated as compared to their adjacent non-tumor gastric tissues by 60%, 61%, 58%, and 62%, respectively." (PMID 29179449, 2017). "Therefore, an antagonist gel that inhibits both CLR/RAMP1 and 2 may be useful for blocking CGRP- and ADM-mediated tumor growth and metastasis in patients." (PMID 36569288, 2022). "In Rag1−/− mice co-transplanted with RAMP1-expressing and -non-expressing CD8+ T cells, we found that within the same tumour, the relative proportion of intratumoral PD-1+LAG3+TIM3+ CD8+ T cells was lower in Ramp1−/− CD8+ T cells." (PMID 36323780, 2022).